TNF (tumor necrosis factor)
Diseases named in the same sentence as TNF in open-access papers (continued):
Sharing a sentence is not in itself a finding about the gene and the disease.
cognitive decline (continued). "In particular, cohort studies have indicated that IL-1β, IL-6 and TNFα are involved in the alteration of nutritional status, poor physical performance, loss of muscle strength, cognitive decline, and cardiological, neurological and vascular events." (PMID 34835952, 2021). "Animal studies have shown that peripheral TNF-α can cause neuronal inflammation and lead to cognitive decline by inducing the release of IL-1 in the brain." (PMID 34540188, 2021). "Proinflammatory cytokines, such as IL-1, IL-6 and TNFα, are also known to have a strong association with cognitive decline in humans and animal models." (PMID 30858535, 2019). "In the baseline group, high levels of TNF-α was associated with a four-fold enhancement in the rate of cognitive decline." (PMID 30930767, 2019). "Systemic inflammation leading to increased TNFα is associated with disease progression/cognitive decline in AD patients, and systemic challenge, such as administration of lipopolysaccharide (LPS), can provoke waves of TNFα expression in the rodent brain." (PMID 28947966, 2017). "Patients with AD have higher plasma levels of cytokines, such as interleukin (IL)-6 and IL-1β, than healthy controls, while in patients with mild to moderate AD, elevation in serum tumor necrosis factor (TNF)-α is associated with cognitive decline." (PMID 27688126, 2016). "Increased circulating pro-inflammatory cytokines have been associated with the neurodegenerative conditions of Alzheimer’s disease and Parkinson’s disease and more specifically TNF-α has been linked with the accelerated progression of cognitive decline." (PMID 23840908, 2013). "Elevated IL-6 has been linked with reduced hippocampal volume and cognitive decline in the elderly while studies of depression have implicated IL-1β, TNF-α and IL-6." (PMID 23840908, 2013). "Extensive research has found that pro-inflammatory cytokines including IL-1β, IL-6 and TNF-α are strongly associated with cognitive decline and motor retardation particularly amongst elderly populations." (PMID 21799922, 2011). "IFNγ, as an important cytokine, can enhance the activation state of microglia, leading to the release of inflammatory mediators such as TNF-α, interleukin-1 beta (IL-1β), and nitric oxide, all of which may cause neuronal damage and cognitive decline." (PMID 39076206, 2024). "Indeed, activated microglia are implicated in cognitive decline in AD through loss of synapses and the sustained secretion of neurotoxic cytokines, including TNF-α and IL-1β." (PMID 37762479, 2023). "Particularly, TNF-α has been considered an immune-mediated factor of the sphingolipid signaling pathway in AD and has been associated with synaptic dysfunction in AD-related cognitive decline." (PMID 37095548, 2023). "TNF-α invariably shows an age-related upregulation and was associated with frailty, cardiovascular events and rapid cognitive decline in elderly subjects, but high levels of TNF-α were found to be correlated with mortality in very old subjects in one study, but not in another one." (PMID 36769039, 2023). "Neuroinflammation is closely linked to peripheral immune activation, and cognitive decline is associated with increased peripheral inflammation, and pro-inflammatory cytokines, such as interleukin-1β (IL-1β), interleukin-6 (IL-6) and tumor necrosis factor-α (TNF-α)." (PMID 37921870, 2023). "Also, elevated serum TNF-α is associated with an increased rate of cognitive decline in patients with AD." (PMID 36578022, 2022). "In addition, alterations in several inflammatory markers, such as TNF-α-related cytokines levels in plasma, have been reported to be associated with cognitive decline in AD." (PMID 33132899, 2020). "In line with this, the whole‐brain levels of the pro‐inflammatory cytokines IL‐1β and TNF‐α, which have both been associated with the progression of Aβ deposition, neurodegeneration, and cognitive decline in AD, were reduced in APP/PS1‐Stat3KO compared to APP/PS1‐Stat3WT mice." (PMID 30617153, 2019).
cognitive decline (continued). "In conclusion, our studies have proven that scutellarin alleviates Alzheimer’s-like pathology and cognitive decline by reducing Aβ levels in the brain and plasma, decreasing Aβ plaque associated gliosis and levels of proinflammatory cytokines TNF-α and IL-6, and attenuating neuroinflammation." (PMID 29642616, 2018). "Interestingly elevated systemic fibrinogen, TNFα and IL-6 in mid-life have also been linked with brain shrinkage, cognitive decline, and AD in later life." (PMID 30524237, 2018). "A decrease in cognitive decline in AD patients following systemic inflammation has been seen to last at least 6 months after the event and has also been linked to higher serum levels of TNF." (PMID 28284226, 2017). "Interestingly, increased serum TNF levels due to systemic inflammation have been associated with an increased cognitive decline in AD and PD suggesting a link between systemic inflammation and neurodegeneration." (PMID 25834699, 2015). "Moreover, P. gingivalis periodontal infection could cause cognitive decline by releasing proinflammatory cytokines, including tumor necrosis factor-alpha (TNF-α), interleukin (IL)-6, and IL-1β, in the brain." (PMID 40612448, 2025). "In current study, elevated levels of IL-6, IL-1β, and TNF-α were positively associated with poorer cognition, especially in aged LPS and LPS-EE mice, demonstrating that increased systemic inflammation is closely related to cognitive decline during the accelerated aging." (PMID 36479357, 2022). "Hence, this study further supported the hypothesis that acute episodes of systemic inflammation, particularly, TNF-α, are linked to long-term cognitive decline in AD." (PMID 29707568, 2018). "In this study, the absence of association between the TNF-308 (rs1800629 G>A) polymorphism and cognitive decline could be attributed to the low allele frequency of the TNF-308 G/A polymorphism in our study population, which comprises mainly of Chinese patients." (PMID 27701469, 2016). "Our findings confirm that TNF-α is a crucial inflammatory marker influencing metabolic disturbances and cognitive decline in middle-aged women." (PMID 40137151, 2025). "Studies indicate that glial cell-derived inflammatory cytokines (e.g., IL-1β, TNF-α) trigger neuronal apoptosis through modulation of Bcl-2 family proteins and caspases, ultimately driving cognitive decline." (PMID 41291751, 2025). "In AD progression, MG are activated to release cytokines (TNF-α, IL-1β, IL-6) and ROS, which exacerbate neuronal damage, impair synaptic function, and lead to cognitive decline." (PMID 41256774, 2025). "Increased levels of systemic inflammatory cytokines, such as TNF-α and IL-1ß, can result in endothelial dysfunction, including blood–brain-barrier dysfunction, leading to cognitive decline." (PMID 39085534, 2025). "The strongest associations with cognitive decline in AD and MCI were detected for IL-1β and TNF-α levels." (PMID 40711681, 2025). "TNF-α is typically low in healthy adults but significantly elevated in AD, where it accelerates cognitive decline." (PMID 40859005, 2025). "They found that patients with persistently elevated IL-6 and TNF-alpha levels were more likely to experience significant cognitive decline in addition to physical disability." (PMID 39859987, 2025). "Inflammatory cytokines (e.g., IL-6, TNF-α) can negatively affect neuronal function, leading to cognitive decline." (PMID 40868579, 2025). "Alzheimer’s patients who have elevated levels of TNF-α in their blood and experience intermittent systemic infections experience a significant acceleration in cognitive decline." (PMID 41009474, 2025). "Elevated OS markers such as 8-hydroxydeoxyguanosine (8-OHdG) correlate with cognitive decline in AD, while ROS overproduction activates pro-inflammatory cytokines (IL-1β, TNF-α), amplifying neuroinflammation via microglial activation." (PMID 40606501, 2025).
cognitive decline (continued). "Persistent neuroinflammation, marked by elevated proinflammatory cytokines such as interleukin (IL)-6, IL-1β, and tumor necrosis factor-alpha (TNF-α), is strongly implicated in synaptic dysfunction, neurotransmitter dysregulation, and cognitive decline." (PMID 41020008, 2025). "Emerging evidence strongly suggests that inflammatory pathways (notably upregulation of pro-inflammatory factors such as NF-κB, TNF-α, and IL-6) are key contributors to cognitive decline." (PMID 40520187, 2025). "Concurrently, Aβ oligomers affected the neurons and the microglia to upregulate TNF-α levels and lead to cognitive decline." (PMID 38091207, 2024). "-MaR1 improved cognitive decline by reducing pro-inflammatory cytokines (TNF-α, IL-6, MCP-1) and increasing anti-inflammatory cytokines (IL-2, IL-10) levels." (PMID 39452854, 2024). "It is well-known that an increase in pro-inflammatory markers such as TNF-α is involved in the cognitive decline process of individuals with DS." (PMID 38576478, 2024). "While some studies have shown associations between inflammatory biomarkers like CRP, IL-6, and TNF-α with cognitive decline and neurodegenerative diseases, their utility as predictive factors remains uncertain." (PMID 38891863, 2024). "Chronic neuroinflammation, marked by elevated pro-inflammatory cytokines such as IL-6 and TNF-α, plays a pivotal role in accelerating cognitive decline." (PMID 39767653, 2024). "Proinflammatory cytokines, such as IL-1β and TNF-α, have been reported to induce neuroinflammation and neurotoxicity in the brain and result in cognitive decline." (PMID 38191451, 2024). "In this regard, it has previously been found that patients with systemic inflammatory events and elevated plasma TNF-α levels show a 10-fold higher rate of cognitive decline over a 6-month observation period." (PMID 38397814, 2024). "The upregulation of inflammatory cytokines, such as tumor necrosis factor alpha and interleukin 6, is a significant factor in cognitive decline." (PMID 39021595, 2024). "To evaluate the contribution of neuroinflammatory processes in cognitive decline in individuals with DS, we measured TNF-α plasma concentrations, a well-known pro-inflammatory mediator involved in AD-related cognitive decline in DS." (PMID 38576478, 2024). "In alignment with expectations, our investigation revealed elevated TNF-α concentrations in older adult individuals with DS and AD-related cognitive decline (p < 0.01)." (PMID 38576478, 2024). "With age, microglial cells the resident innate immune cells of the central nervous system—become chronically active, leading to sustained release of pro-inflammatory cytokines such as IL-6 and TNF-a, known as contributors to cognitive decline." (PMID 39446794, 2024). "Through suppressing HMGB1, the levels of TNF-α, IL-1β, and IL-6 decreased, and hippocampal atrophy and cognitive decline were attenuated in the CCH model of mice." (PMID 38231472, 2024). "This activation releases pro-inflammatory cytokines, such as TNF-α, IL-6, and IL-1β, which worsen neuroinflammation, contribute to neuronal damage, and promote cognitive decline." (PMID 38963109, 2024). "Specifically, TNF-α plays a pivotal role in cognitive decline by facilitating IRS1 phosphorylation through JNK activation, thereby modulating or inhibiting the IR in hippocampal neurons." (PMID 37762479, 2023). "In animal models of AD, TNFα favoured microglial activation and accumulation of β-amyloid plaques, synaptic dysfunction, and cognitive decline." (PMID 37332353, 2023). "Both TNF-a and MDA have been associated with increased delirium and cognitive decline postoperatively." (PMID 37038219, 2023). "Studies have shown that TNF-α in the circulation is a central mediator of neuroinflammation and predicts cognitive decline in AD patients." (PMID 38082215, 2023). "Chronic neuroinflammation has been linked to cognitive decline in VCID patients, with high expression of IL-1β and TNF-α in the hippocampus." (PMID 37208759, 2023).
cognitive decline (continued). "Changes in serum levels of IL-6, IL-1β, and TNF-α reflective of systemic inflammation and their correlation with cognitive decline during accelerated aging were similar to those of hippocampal NGPF2." (PMID 36479357, 2022). "A recent study explored the upregulation of inflammatory biomarkers such as TNF-α and IL-1β in people with cognitive decline." (PMID 35745147, 2022). "There were not any significant correlations between the serum levels of TNF-a and cognitive decline measured with MMSE and ACEIII." (PMID 36613708, 2022). "These IL-10(-/-) mice also produce more pro-inflammatory cytokines IL-1β, IL-6 and TNF-α in the plasma, suggesting IL-10 inhibits cognitive decline via its propensity to mitigate inflammation." (PMID 35308288, 2022). "High systemic TNF-α levels correspond with rapid cognitive decline over 6 months in AD patients, thus dietary modulation of this cytokine should be further investigated." (PMID 36248655, 2022). "TNFα is one of the most well-defined cytokines during AD pathogenesis and is correlated with cognitive decline, neuronal toxicity, and cerebral apoptosis." (PMID 35269588, 2022). "Overexpressed cytokines, such as tumor necrosis factor (TNF)-α, cross the blood–brain barrier, increase neuroinflammation, interfere with neuronal activity, and eventually lead to cognitive decline." (PMID 35945306, 2022). "TNF-α is a proinflammatory cytokine involved in mediating inflammatory responses and cognitive decline." (PMID 34199148, 2021). "Previous studies have shown that TNF-α and IL-6 levels increased postoperatively and were closely related to cognitive decline." (PMID 33836651, 2021). "Direct application of TNF-α to cell culture preparations, or CNS administration of TNF-α, increased Aβ production, tau phosphorylation, and synaptic dysfunction, and accelerated disease progression and cognitive decline." (PMID 34972522, 2021). "Systemic inflammatory markers such as C-reactive protein, tumor necrosis factor-alpha (TNF-a), and interleukin-6 (IL-6) are all implicated in cognitive decline." (PMID 34439769, 2021). "Though many of these trials would suggest a lack of conventionally defined efficacy as maintenance therapy, initial trials with anti-TNF medications have demonstrated the potential to attenuate cognitive decline in many patients." (PMID 34112182, 2021). "Interestingly, it has recently been shown that RA patients treated with TNF-α-inhibiting biological therapies showed a 50% decreased risk of developing cognitive decline, where this may be due to the fact that TNF-α is involved in the physiopathology of dementia, as well as in that of RA." (PMID 33530359, 2021). "In patients with cirrhosis and HE, proinflammatory cytokines, such as tumor necrosis factor α (TNF-α), interleukin 1β (IL-1β), and interleukin 6 (IL-6), modulate and have synergistic effects with ammonia during cognitive decline." (PMID 34937168, 2021). "The markers related to cognitive decline were classified into the following two groups: Neuroinflammatory markers: IL-1β, IL-6, tumor necrosis factor-α (TNF-α) and genetic markers (Bdnf, Arc, Egr1) which were estimated in brain regions." (PMID 33918576, 2021). "Anesthesia/surgery can induce the innate immune system response and microglia activation, leading to the synthesis and release of inflammatory cytokines (e.g., TNF-α, IL-1β, and IL-6) and cognitive decline." (PMID 33541361, 2021). "Serum concentrations of TNF-α are also found to be upregulated in AD and in MCI34, and increased TNF-α serum levels have an associated four-fold greater rate of cognitive decline than AD patients with low baseline TNF-α35." (PMID 33850164, 2021). "Collectively, these studies suggest an enduring link between high serum and CSF TNF-α levels, inflammation, and progressive cognitive decline in AD." (PMID 33850164, 2021). "Bifidobacterium longum NK46 suppresses cognitive decline and hippocampal TNF-α expression in aged and 5XFAD transgenic mice." (PMID 34667205, 2021).
cognitive decline (continued). "Our recent clinical research showed that the intake of propolis, a resinous mixture produced by honey bees, for 2 years prevented the cognitive decline in elderly individuals by decreasing the serum levels of IL-1β, IL-6, and TNF-α." (PMID 33716675, 2021). "Inflammatory cytokines, including IL-6, IL-10, CRP, MCP-1, ICAM-1, and TNF-α, play an important role in the development of poststroke cognitive decline." (PMID 35111122, 2021). "HMGB1 suppression with CRISPR/Cas9 knockout plasmid restored TNF-α, IL-1β, and IL-6 and attenuated hippocampal atrophy and cognitive decline." (PMID 32245271, 2020). "Further follow up of this cohort will determine the exact relationship between TNF-α levels, performance on this task and later cognitive decline." (PMID 33424582, 2020). "Previous evidence suggests that peripheral TNF, either related to acute or chronic inflammatory processes, can predict cognitive decline in AD." (PMID 32171317, 2020). "P. gingivalis IgG concentration, TNF-α, and IL-10 correlated with the progress of cognitive decline." (PMID 32054121, 2020). "TNF-α and IL-6 influence the onset of frailty and cognitive decline, and CRP levels link muscle quality with cognitive function." (PMID 32257550, 2020). "As people age, proinflammatory markers such as C-reactive protein (CRP), interleukin (IL)-6 and -1 beta, and tumor necrosis factor alpha (TNF-alpha) increase and are related to cognitive decline." (PMID 32509348, 2020). "An increase in the serum level of TNF-α and a two-fold increase in the rate of cognitive decline over 6 months were observed in around half of all study participants." (PMID 30930767, 2019). "Overall, neuronal dysfunction and subsequently cognitive decline is perpetuated by inflammatory cytokines, such as IL-1β, IL-6 and TNF-α." (PMID 30374291, 2018). "For example, in mice, TNF-α injection induces cognitive decline via increasing the expression of COX-2." (PMID 29245902, 2017). "In a clinical population of AD patients, elevated baseline systemic TNF-α, when combined with an observed systemic inflammatory event (SIE), was associated with a 10-fold greater rate of cognitive decline over 6 months." (PMID 27633985, 2017). "Reports demonstrate that inflammatory responses mediated by Aβ peptides in the brains of AD were significantly elevated, such as IL-1β and TNF-α, which is believed to mediate neuronal injury and finally, cognitive decline." (PMID 25586060, 2016). "TNF-α and IL-1β as pro-inflammatory cytokines, have been related to the cognitive decline characteristic of AD and proposed to be valuable biomarkers for this disorder." (PMID 25586060, 2016). "This is consistent with prior data demonstrating that the TNF-α level in the serum of AD patients is predictive of accelerated cognitive decline." (PMID 25802557, 2015). "A previous investigation revealed that HupA inhibited the overexpression of TNF-α and improved the cognitive decline in a rat model of cerebral hypoperfusion, which was, in part, in agreement with our current findings." (PMID 24857910, 2014). "TNF-α has been previously reported as an early marker for mediating cognitive decline after peripheral sterile injury contributing to the BBB opening during systemic inflammation and neurodegeneration." (PMID 25170959, 2014). "Treatment of mice with prophylactic administration of cholinergic agonists or a monoclonal antibody to TNF-α prevented neuroinflammation in the hippocampus and cognitive decline following surgery." (PMID 23029109, 2012). "Increase in the serum levels of TNF-alpha following acute inflammatory events was found to correlate with a 2-fold increase in the rate of cognitive decline over a 6-month period in AD patients." (PMID 22191060, 2011). "Inflammation was related to the onset of cognitive decline and also correlated with disease progression by measurements of serum TNFα and the TNFα/IL1-β ratio." (PMID 21876809, 2011).